HLA-DRB1 (major histocompatibility complex, class II, DR beta 1)
Diseases named in the same sentence as HLA-DRB1 in open-access papers (continued):
Sharing a sentence is not in itself a finding about the gene and the disease.
Autoimmunity (53 papers, 2006 to 2025). The occurrence of an immune reaction against the organism's own cells or tissues. "It is well documented that the HLA-DRB1 genotype plays an important role in the development of autoimmunity, and consequently, the HLA-DRB1 risk alleles in our cohort are highly represented." (PMID 39188918, 2024). "It will be important going forward to carefully interrogate the mechanisms by which HLA-DRB1*03 and C4A deficiency contribute to autoimmunity and IIM." (PMID 36171069, 2023). "The authors observed an association between the ATD disease and H. pylori-positive status, but only concomitantly with the presence of the HLA-DRB1*0301 allele, a genetic marker of autoimmunity." (PMID 35799701, 2022). "HLA-DRB1*13, which is considered as protective for autoimmunity in general, is also negatively associated with IgG4-AID." (PMID 35654912, 2022). "The patient presented an autoimmunity-associated HLA haplotype (HLA-A*02/HLA-B*08/HLA-C*07/HLA-DRB1*03) and experienced an increase in activated CD8 T-cells along the treatment." (PMID 34200673, 2021). "For example, HLA-DRB1 shared epitope alleles show strong gene-environment interactions with smoking and are found exclusively in those with anticitrulline autoimmunity." (PMID 27050433, 2016). "Non-traditional risk factors associated to CVD in this population were HLA-DRB1 shared epitope alleles, rheumatoid factor, markers of chronic inflammation, long duration of RA, steroids, familial autoimmunity, and thrombogenic factors." (PMID 23193471, 2012). "Most recently, a close association of the production of anti-CCP antibodies and HLA-DRB1 has been described, indicating the importance of antigen presentation in the induction of autoimmunity." (PMID 16469113, 2006). "In addition, HLA-DRB1*14, a known genetic susceptibility factor for autoimmunity, is also associated with IgG4 autoimmunity, as is the HLA- DQB1*05-DRB1*14 haplotype." (PMID 35654912, 2022). "Additionally, genetic susceptibility may play a role; specific HLA alleles (e.g., HLA-DRB1*04:02) could enhance susceptibility to biologic-induced autoimmunity by influencing antigen presentation efficiency." (PMID 41000395, 2025). "It is believed that adjuvants such as aluminum salts, emulsions, oils, spike (S) protein, Toll-like receptor agonists, mRNA vaccine lipids, and polyethylene glycol could promote immune hyperactivation with autoimmunity in genetically susceptible individuals (HLA-DRB1)." (PMID 39044822, 2024). "Besides, HLA-DRB1 is the locus most associated with autoimmunity." (PMID 34413879, 2021). "Despite of the fact that the origins of autoimmunity and the induction of the production of brain auto-antibodies in autism are unknown, the major histocompatibility complex genes and their products (e.g., HLA-DRB1 and C4B null alleles) might be involved." (PMID 21696608, 2011). "The progression rate to T1D was assessed according to sex, relationship with the proband, age at autoimmunity detection, type/number of autoantibodies, and HLA-DRB1 genotype." (PMID 39188918, 2024). "Donor 5443 was unusual, in that this donor was homozygous for a total of 7 out of 9 HLA alleles: HLA-B, HLA-C, HLA-DRB1, DRB4, DQA1, DQB1 and DPA1, with specific HLA alleles more predisposed to autoimmunity." (PMID 36936963, 2023). "As vimentin is a known antigenic target in B-cell-mediated autoimmunity, we investigated in situ humoral anti-vimentin responses in pulmonary sarcoidosis and their relationship with HLA-DRB1*03." (PMID 30038611, 2018). "In the landmark models for the association of HLA-B*35, HLA-DRB1*0701, and HLA-A*02 with RFS or OS, only autoimmunity was found statistically significant (P < .0001)." (PMID 20549830, 2010). "The frequency of the high-risk HLA-DRB1 genotype (DR3/DR4) was shown to be significantly higher among autoimmune-positive siblings compared with siblings who did not develop autoimmunity throughout the study (43% vs. 0%, p < 0.01)." (PMID 39188918, 2024).
Autoimmunity (continued). "As HLA-DRB1 polymorphism and MBL deficiency are both associated with autoimmunity and with RPL separately, the natural question arises whether autoantibody development is an intermediate or causal factor between the immunogenetic profile and occurrence of RPL." (PMID 36776871, 2023). "Interestingly, when |Δβ| ≥ 0.1 (simultaneously p < 0.01), 4 of the 28 DMGs—HLA-DPB2, HLA-DRB1, PPP2R5C, and LTF, which all mapped from more than one CpG site—are all associated with autoimmunity." (PMID 34539625, 2021). "Of the 28 DMGs, HLA-DPB2, HLA-DRB1, PPP2R5C, and LTF were associated with autoimmunity." (PMID 34539625, 2021). "To test this, we analyzed association between non-vitiligo autoimmunity and HLA-DRB1*13:01 and rs145954018." (PMID 30674883, 2019). "The HLA-DRB1 locus is known as the most important genetic contributor for the risk of RA, but is not sufficient to drive autoimmunity and additional genetic and environmental factors are involved." (PMID 25138370, 2014). "However, this does not mean that HLA-DRB1 is irrelevant in the development of diabetes, as demonstrated in this study by the higher frequency of high-risk HLA-DRB1 genotypes in siblings who developed autoimmunity compared with those who did not." (PMID 39188918, 2024). "However, the frequencies of CTLA-4 and HLA-DRB1 were not significantly different between the autoimmune FXIII deficiency cases and those reported by the database." (PMID 34506591, 2021). "Moreover in addition to their protective effect in RA, PE-coding HLA-DRB1 alleles have been found to decrease disease risk in many other autoimmune conditions that do not share putative antigens with RA." (PMID 33510427, 2021). "HLA-DRB1*10:01/HLA-DQB*05:01 alleles in 87%.No history of autoimmunity or cancer in 91%." (PMID 34108243, 2021). "Shared alleles influence antigen presentation and immune system tolerance in autoimmunity (HLA-DRB1*08 in PBC; HLA-DRB1*1104 in SSc)." (PMID 40351968, 2025). "Among 41 patients with MD, 20% of patients showed autoimmunity to type II collagen, and these patients demonstrated a higher rate of the specific HLA-DRB1 genotype of HLA-DRB1*0405 than other patients (63% vs. 12%)." (PMID 34884398, 2021). "Thus, if the ability to recognize and present a high range of peptides is coupled with a higher cross-reactive capacity of the HLA-DRB1*15:01 allele compared to other alleles, this could increase the risk of developing autoimmunity, rather than providing effective protection against the virus." (PMID 39044822, 2024). "The maternal HLA-DRB1*0301 (HLA-DR3) and HLA-DRB1*0401/040X (HLA-DR4), belonging to the major histocompatibility complex (MHC) class II reveals the critical role of autoimmunity in the pathogenesis of the PG due to their predominant correlation with the disease." (PMID 39598226, 2024). "HLA-DRB1*03 and *04, which are often associated with autoimmunity, did not correlate with IgG4-AID, with the notable exception of pemphigus, which showed a strong association with HLA-DRB1*04." (PMID 35654912, 2022). "Our results show that, unlike the previously reported HLA-DR-dependent susceptibility to MBP-, PLP-, or MOG-induced EAE, the pathogenic autoimmunity against PLP, as well as against MOBP, was dependent on HLA-DQB1*0602 rather than HLA-DRB1*1501." (PMID 22316121, 2012). "With the 16.586 different ligands of the HLA-DRB1*03:01/HLA-DRB3*02:02 B cell ligandome now publicly available, additional analyses can be performed related to several immunological questions regarding the role of HLA-DR3 in allergy, autoimmunity, infection and transplant rejection." (PMID 31520135, 2019).
COVID-19 (53 papers, 2020 to 2025). A disease caused by infection with severe acute respiratory syndrome coronavirus 2. "In this study, HLA-DRB1*11 allele was associated with a protective effect against severe and critical forms of COVID-19, and this association remained significant even after applying the Bonferroni correction." (PMID 40508150, 2025). "Our findings also revealed a significant association between the HLA-DRB1*15 allelic group and an increased risk of developing severe forms of COVID-19, with the association remaining significant after Bonferroni correction." (PMID 40508150, 2025). "In an Italian cohort, the HLA-DRB1*15:01 allele was significantly associated with severe and critical COVID-19 cases when compared to a control group of healthy individuals." (PMID 40508150, 2025). "HLA-DRB1*11 was also found to be independently associated with COVID-19(+) and a 40% decrease in the probability of COVID-19(+) in kidney transplant recipients." (PMID 37845715, 2023). "Analysis of 32 common HLA alleles at four loci revealed a significant association between HLA-DRB1*09:01 and severe COVID-19, which indicate a potential role for HLA in predisposition to severe COVID-19." (PMID 37853311, 2023). "The aim of the present study was to determine the frequencies of HLA-DRB1*11 and HLA-DRB1*12 allele polymorphisms and their associations with COVID-19." (PMID 37845715, 2023). "Our results showed that HLA-A*11 and HLA-DRB1*14 alleles were more frequently observed in severe COVID-19 cases, while HLA-B*52 was more common in mild cases, which was in agreement with some previous studies." (PMID 38301089, 2023). "Frequency analysis showed that HLA-A*11, HLA-B*38, and HLA-DRB1*14 alleles were significantly associated with severe COVID-19 and HLA-B*52 with mild COVID-19, consistent with some previous studies." (PMID 38301089, 2023). "HLA class I polymorphisms, such as HLA-B*46:01, HLA-B*07:03, and HLA-Cw*08:01, and HLA class II polymorphisms HLA-DRB4*01 and HLA-DRB1*12:02 have been associated with the predisposition to COVID-19." (PMID 35062298, 2022). "Another peptide binding prediction analyses showed that HLA-DRB1*08 alleles were unable to bind any of the viral peptides with high affinity, thus individuals with those alleles were at high risk of severe COVID-19." (PMID 36204639, 2022). "In COVID-19 patients from Italy, the allele frequency distributions for HLA-DRB1*15:01 and DQB1*06:02 showed significant correlations of the minor allele with higher susceptibility to the disease, while DRB1*07:01 on the contrary was negatively associated." (PMID 34070971, 2021). "The current study identified a potential association of the HLA-DRB1*01 allele with COVID-19 susceptibility and severity in a Greek cohort of COVID-19 patients." (PMID 34685388, 2021). "A positive allele association was observed for HLA-DRB1*01 in total COVID-19 patients versus healthy controls." (PMID 34685388, 2021). "Meanwhile, an Iranian study observed a lower frequency of HLA-DRB1*15 in COVID-19 patients compared to healthy controls; however, this allele group was more common in patients exhibiting lymphopenia, a condition frequently associated with severe and critical disease forms." (PMID 40508150, 2025). "Interestingly, in our present study, the HLA-DRB1*03:01 allele was found to be associated with the severe course of COVID-19, and this allele was four times more common in patients with severe COVID-19 than in those with a mild course of infection." (PMID 39768617, 2024). "Genetic association of class II HLA-DRB1*04:01 with hepatitis cases is consistent with the association of this allele with COVID-19 severity, indicating that a dysregulated immune response to the virus may be responsible for hepatitis observed in these cases." (PMID 39653515, 2024). "We found that HLA-A*11 and HLA-DRB1*14 alleles may be susceptibility factors for severe COVID-19, while HLA-B*52 may be a protective factor." (PMID 38301089, 2023).
COVID-19 (continued). "Moreover, patients with a decreased class II HLA-DR cluster 1 showed increased risk of developing severe COVID-19, and in particular rs9271609 (TC genotype) of the HLA-DRB1 was weakly correlated with severe COVID-19." (PMID 36941580, 2023). "The research on the influence of HLA genotype on COVID-19 severity revealed a significant difference in the allele frequency of HLA-DRB1*04:01 in severe patients as compared to the asymptomatic staff group in the European population (5.1% vs. 16.7%, p-value = 0.003 after adjustment for age and sex)." (PMID 36834479, 2023). "However, patients with HLA-DRB1*11/12 genotypes had an approximately 8-fold risk of developing severe forms of COVID-19 (p = 0.048; OR = 7.70 [0.895–66.189])." (PMID 37845715, 2023). "In those who had COVID-19, a slightly lower number of alleles was detected for each of the studied HLA loci than in the control group: 15 for HLA-A* (control 17); 22 for HLA-B* (control 33); and 12 for HLA-DRB1* (control 13)." (PMID 36360904, 2022). "Importantly, allelic genotypes of HLA-DRB1 have been associated with the clinical severity of adult COVID-19 cases, and CD8+ T-cells from critically ill adult COVID-19 patients show upregulation of the HLA-DRB1 gene." (PMID 35770252, 2022). "Reduced allele frequency of HLA-DRB1 has also been observed in severe COVID-19." (PMID 36143338, 2022). "In the Mexican population, HLA-DRB1*01 was negatively associated with COVID-19-associated fatality." (PMID 36366349, 2022). "One of the genetic predisposing factors, besides the expression of ACE 2 and the protein associated with it, can be genotypes HLA-A*02:01 and HLA-A*03:01, associated with a low probability of developing a severe form of COVID-19, and HLA-DRB1*04: 01 associated with asymptomatic infection." (PMID 34832564, 2021). "Similarly, HLA class I molecules, such as HLAB*46:01, HLA-B*07:03, and HLA-Cw*08:01, as well as HLA class II molecules, including HLA-DRB4*01 and HLA-DRB1*12:02, are associated to predisposition to COVID-19, and some of these HLA molecules have been shown to bind to few SARS-CoV-2 peptides." (PMID 35062298, 2022). "Additional studies have also highlighted the possible involvement of the HLA-DRB1*15 allelic group in the severity of COVID-19." (PMID 40508150, 2025). "Results showed that in the COVID-19(+) group, HLA-DRB1*13:02 and HLA-DRB1*13:03 were more frequent in SAT patients." (PMID 41488629, 2025). "Certain HLA-DRB alleles, such as HLA-DRB1*15, are linked to a more severe clinical course of COVID-19." (PMID 41012626, 2025). "We enrolled 92 unvaccinated HLA-DRB1*01:01+ COVID-19 patients, who were genotyped using PCR and divided into six groups, based on the level of severity of their COVID-19 symptoms (from severity 5 to severity 0, assessed at discharge)." (PMID 38605956, 2024). "For MHC class II, the frequency of HLA-DRB1*11:02 was higher in COVID-19 patients compared to controls (2.86% vs. 0.34%, p < 0.001), while the frequency of DQB1*03:03 was lower in the patients group (2.86% vs. 9.04%, p < 0.001)." (PMID 39768617, 2024). "Reduced peptide binding IgG level was observed for severely ill COVID-19 patients and in mock-vaccinated triple transgenic HLA-A*02:01/HLA-DRB1*01:01-hACE-2 mice." (PMID 38318166, 2024). "A recent large-scale WGS association study identified a significant association between the lead SNP rs9271609, located upstream of HLA-DQA1 and HLA-DRB1 in the HLA class II region, and COVID-19 severity." (PMID 38181733, 2024). "An Italian study found that haplotype HLAA*01:01, HLA-B*08:01 and HLA-DRB1*03:01 contributed to the higher COVID-19 mortality in northern Italy." (PMID 36204639, 2022). "Subgrouping of COVID-19 patients in mild and hospitalized further identified a statistically significant increase in HLA-DRB1*01 in mild COVID-19 patients versus controls." (PMID 34685388, 2021).
COVID-19 (continued). "HLA-DRB1*09 was also found significantly increased in COVID-19 patients (p = 0.024, OR = 10.413, CI = 1.152–94.103) but the significance was lost after applying Bonferroni correction (pc = 0.36, NS)." (PMID 34685388, 2021). "Specifically, the frequency of HLA-DRB1*01 was significantly increased in COVID-19 patients (p = 0.002, OR = 2.693, CI = 1.426–5.087) and the significance was maintained after applying Bonferroni correction (pc = 0.03)." (PMID 34685388, 2021). "In the COVID-19 (–) group, HLA-B*35:03, HLA-DRB1*12:01, and HLA-DRB1*14:01 were elevated in SAT patients, suggesting susceptibility alleles may differ based on prior COVID-19 infection." (PMID 41488629, 2025). "In addition, two haplotypes previously related to vaccination were identified HLA-DRB1*01:01-DQA1*01:01-DQB1*05:01 and HLA-DRB1*15:01-DQA1*01:02-DQB1*06:02 linked to low and high COVID-19 vaccination response respectively." (PMID 38637586, 2024). "Moreover, we have demonstrated that the severe course of COVID-19 can be associated with the presence of HLA-B*08:01, C*04:01, DRB1*03:01, and DQB1*03:01, while HLA-DRB1*08:01 appears to be protective." (PMID 39768617, 2024). "Moreover, we demonstrated that the severe symptomatic course of COVID-19 can be associated with the presence of HLA-B*08:01, C*04:01, DRB1*03:01, and DQB1*03:01, while HLA-DRB1*08:01 appeared to be protective against severe COVID-19 disease." (PMID 39768617, 2024). "Interestingly, several other non-celiac-associated HLAs are associated with asymptomatic (HLA-B*15:01, HLA-DRB1*04:01) or milder forms (HLA-B*15, HLA-DRB1*04) of COVID-19." (PMID 38138121, 2023). "In this study, the frequency of HLA-DRB1*14 was significantly higher in severe COVID-19." (PMID 38301089, 2023). "For COVID-19[+] women and COVID-19[-] men, the strongest association is for a missense mutation in HLA-DRB1 (rs767010367), which is not detected in other comparisons." (PMID 34650566, 2021). "Furthermore, alleles HLA-DRB1*01:01, HLA-DRB1*12:01, and HLA-DRB1*14:04 have also been associated with COVID-19 severity in a Chinese population of COVID-19 patients although the statistical significance was not maintained after Bonferroni correction." (PMID 34685388, 2021). "The dominant S166–180-specific TCRα clonotypes in HLA-DPB1*04:01+ individuals are associated with mild COVID-19 disease, while the dominant S751–765-specific or S866–880-specific TCRα clonotypes in HLA-DRB1*15:01+ participants are associated with non-hospitalised COVID-19." (PMID 41034205, 2025). "For example, the HLA-DRB1*04 may predict disease severity in Iranian COVID-19 patients." (PMID 39257586, 2024). "In contrast, HLA-DRB1 overall repertoire did not seem to be associated with either COVID-19 susceptibility or severity, which is consistent with previous studies and compatible with the fact that HLA Class II molecules are less directly involved with initial reactions against viral infections." (PMID 35911710, 2022). "Our cohort comprised 48 individuals who had recovered from COVID-19, with 30 (66.7% of 45) being HLA-DPB1*04:01 positive; and 17 (36.2% of 47) carrying HLA-DRB1*15:01." (PMID 41034205, 2025). "Our analysis revealed a downregulation of FXYD, HLA-DRB1, and RPS20 in memory B cells; MTATP8 and HLA-DQA1 in naïve cells; RPS4Y1 in activated B cells; and IGHV3-73 in plasma cells in COVID-19 patients." (PMID 36826040, 2023). "Differential expression analysis in the scRNA-seq revealed that MHC class II genes, such as HLA-DRB5, HLA-DPB1, HLA-DPA1, HLA-DRB1, and HLA-DRA, were downregulated in convalescent COVID-19 individuals." (PMID 35464396, 2022). "We identified SNPs in Class II HLA genes, HLA-DRB1, and HLA-DQB1 previously noted to be strongly repressed in a dominant population of dendritic cells, in acute cases of COVID-19, in cohort 1 and 2, respectively." (PMID 36143338, 2022).